KLF2 (KLF transcription factor 2)
Diseases named in the same sentence as KLF2 in open-access papers (continued):
Sharing a sentence is not in itself a finding about the gene and the disease.
breast tumor (2 papers, 2015 to 2023). "Our findings indicate that KLF2 acts as a tumor suppressor and is associated with diverse immune infiltration cells, potentially affecting the breast tumor immune microenvironment by enhancing dendritic cell activation." (PMID 37123417, 2023). "KLF2 expression is associated with diverse immune infiltration cells, and may impact the breast tumor immune microenvironment by regulating dendritic cell activation." (PMID 37123417, 2023). "Two independent expression array profiles deposited in OncomineTM Compedia Bioscience documented that the level of KLF2 mRNA is markedly lower in human breast tumors vs. normal breast tissue." (PMID 26416422, 2015). "Analysis of a qPCR array consisting of cDNA derived from samples of normal breast and various stages of human breast tumors (OriGene) showed that downregulation of KLF2 during disease progression is correlated with a marked decrease in the ratio of CRABP2 and FABP5 mRNAs." (PMID 26416422, 2015).
bronchopulmonary dysplasia (2 papers, 2022). Bronchopulmonary dysplasia is a chronic respiratory disease that results from complications related to lung injury during the treatment of infant acute respiratory distress syndrome in low-birth-weight premature infants or from abnormal lung development in older infants. "In summary, our findings indicate that simvastatin could downregulate NLRP3 inflammasome activation and attenuate lung injury in hyperoxia-induced bronchopulmonary dysplasia via KLF2-mediated mechanism." (PMID 35509841, 2022). "Simvastatin could downregulate NLRP3-related pyroptosis and attenuate lung injury in hyperoxia-induced bronchopulmonary dysplasia via a KLF2-mediated mechanism." (PMID 36685920, 2022). "Consequently, we hypothesized that simvastatin could protect against hyperoxia-induced bronchopulmonary dysplasia by suppressing NLRP3 activation and acting as an anti-inflammatory and antioxidant agent by upregulating KLF2 expression." (PMID 35509841, 2022).
Cerebral ischemia (2 papers, 2021 to 2022). Restriction of arterial blood supply to the brain associated with insufficient oxygenation to support the metabolic requirements of the tissue. "More importantly in the present context, over-expression of KLF2 can improve ischemic liver injury, while KLF2 is also implicated in angiogenesis after cerebral ischemia." (PMID 35091544, 2022). "Several KLF family members, namely KLF2, 4, 5, 6, and 11, have been specifically linked to cerebral ischemia pathogenesis." (PMID 33627658, 2021). "This is particularly in line with a prior study illustrating that KLF2 improves ischemic liver injury and cerebral ischemia." (PMID 35091544, 2022).
cervical cancer (2 papers, 2021). A primary or metastatic malignant neoplasm involving the cervix. "For example, recruited EZH2 by long non-coding RNA (lncRNA) LINP1 could contribute to reduced expression of KLF2 in cervical cancer." (PMID 34462420, 2021). "In cisplatin-resistant prostate and cervical cancer cells, lovastatin overcomes resistance by upregulating tumor suppressor genes such as Ras homolog family member B (RHOB) and kruppel-like factor 2 (KLF2) and 6 (KLF6)." (PMID 34065757, 2021).
endotoxemia (2 papers, 2024). "In a mouse and cell culture model of endotoxemia, this study specifically looks at the implication of AMPK activation, performed by metformin, on histone deacetylases (HDACs) and Kruppel-like factor 2 (KLF2)." (PMID 38791227, 2024).
fibrosis (2 papers, 2023 to 2024). the formation of excess fibrous connective tissue in an organ or tissue in a reparative or reactive process. "The antioxidative effect of SIM in this fibrosis liver microtissue model is probably induced by KLF2‐NO signalling in LSECs which upregulates the expression of Chemokine (C‐X‐C motif) ligand 16 (CXCL16) on LSECs." (PMID 38984945, 2024).
gastric tumor (2 papers, 2017 to 2021). "It has been reported that the expression of KLF2 protein is lower in gastric tumors, and KLF2 overexpression markedly enhanced cell apoptosis, and induced cell cycle arrest." (PMID 33732285, 2021). "Here we show that the expression of KLF2 protein was lower in gastric tumors when compared with adjacent normal tissue." (PMID 29245984, 2017). "In the present research, we observed that KLF2 was remarkably reduced in gastric tumors, clinical and laboratory findings clearly showed that KLF2 acts as a tumor suppressor in human GC." (PMID 29245984, 2017). "We found that KLF2 protein expression was downregulated in gastric tumor tissues compared with the paired adjacent normal tissues." (PMID 29245984, 2017). "Mechanically, the mRNA and protein level of PTEN was reduced in KLF2 deficient cells and xenograft tumors, suggesting that PTEN/AKT signaling was involved in the gastric tumor inhibitory effect of KLF2." (PMID 29245984, 2017). "We found that KLF2 expression was lower in gastric tumor samples (n = 249, 5.588±0.06843, SEM) compared with normal samples (n = 33, 6.598±0.2504, SEM) (p < 0.001)." (PMID 29245984, 2017). "Moreover, downregulated KLF2 expression in primary gastric tumor was closely correlated with patients’ survival." (PMID 29245984, 2017).
heritable pulmonary arterial hypertension (2 papers, 2020 to 2024). Heritable pulmonary arterial hypertension (HPAH) is a form of pulmonary arterial hypertension (PAH), occurring due to mutations in PAH predisposing genes or in a familial context. "A missense mutation in KLF2 has been identified in heritable pulmonary arterial hypertension (HPAH), highlighting its significant role in PH progression." (PMID 38741032, 2024). "Recently, a missense mutation in the transcription factor Krüppel-like factor 2 (KLF2) gene was identified in a family with autosomal heritable pulmonary arterial hypertension (HPAH), suggesting that KLF2 signalling may be compromised in the disease." (PMID 32132543, 2020).
hypertrophic cardiomyopathies (2 papers, 2024 to 2025). "For hypertrophic cardiomyopathy, the analysis showed a direct interaction, specifically co-expression and text mining, between IL-6 and KLF-2, KLF-4, and KLF-6." (PMID 38672763, 2024).
hyperuricemia (2 papers, 2023 to 2025). An abnormally high level of uric acid. "Furthermore, hyperuricemia suppresses vascular endothelial growth factor-A (VEGFA) by negatively regulating miR-92a, thereby increasing Kruppel-like factor 2 (KLF2) expression, which impairs endothelial cell proliferation and repair capacity." (PMID 41166265, 2025). "Furthermore, the down-regulation of miR-92a is involved in the KLF2-VGEFA axis and the angiogenesis in hyperuricemia, while our results revealed significantly increased expression of miR-92a by the treatment of noni fruit juice." (PMID 37426193, 2023).
infarct (2 papers, 2020 to 2021). "Silencing of MALAT1 using MALAT1‐locked nucleic acid GapmeR significantly attenuated KLF2 and CD31 protein expression after infarction induced by HBO‐induced exosomes." (PMID 32939962, 2020). "Expression of krüppel‐like factor 2 (KLF2) and CD31 was significantly decreased after infarction and HBO‐induced exosomes significantly reversed the expression." (PMID 32939962, 2020).
Insulin resistance (2 papers, 2020 to 2025). Increased resistance towards insulin, that is, diminished effectiveness of insulin in reducing blood glucose levels. "Meanwhile, myeloid-specific KLF2 has been identified as an essential regulator of obesity, implicated in feeding, weight gain, and insulin resistance." (PMID 39269539, 2025). "Preliminary studies suggest that the epigenetic signature of insulin resistance may target endothelial expression of KLF2." (PMID 39269539, 2025).
intracerebral hemorrhage (2 papers, 2021 to 2022). A cerebrovascular disorder characterized by bleeding into one or both cerebral hemispheres including the basal ganglia and the cerebral cortex.
liver cirrhosis (2 papers, 2012 to 2023). "However, it was reported that pathological hepatic hemodynamic variations occurring during liver cirrhosis development caused a 6-fold increase of KLF2 protein levels in vivo." (PMID 22715381, 2012). "Obviously, the expressions of PPP1R12A, SP1 and SMARCAD1 in HCC tissues were higher than those in the liver cirrhosis tissues, which were opposite to the expression trend of KLF2 in HCC." (PMID 37386390, 2023).
liver inflammation (2 papers, 2016 to 2018). "This was evidenced by down-regulation of the KLF2 vasoprotective pathway, impaired vasodilatory capability and endothelial activation, altogether leading to increased hepatic vascular resistance and liver inflammation, with significant leukocyte infiltration, oxidative stress and cell death." (PMID 26905693, 2016).
lung diseases (2 papers, 2020 to 2022). "KLF2 expression has been significantly reduced in many lung diseases, such as influenza virus and lipopolysaccharide-induced ALI, and KLF2 overexpression can significantly improve ALI." (PMID 35509841, 2022).
myocarditis (2 papers, 2013 to 2018). Myocarditis is a condition that is characterized by inflammation of the heart muscle (myocardium). "It has moreover been shown that ectopic expression of KLF2 is sufficient to reduce pathogenic responses in a murine model of myocarditis." (PMID 24155966, 2013). "Studies in mouse have demonstrated a potential role for statin-induced KLF2 expression in protecting against diabetic vascular reactivity and inflammation, as well as myocarditis." (PMID 29459900, 2018). "Furthermore, statin-induced KLF2 expression in effector T cells reduces inflammation in a myocarditis model, an effect that is likely related to diminished interferon-γ production." (PMID 29459900, 2018).
neuroblastoma (2 papers, 2009 to 2013). Neuroblastoma (NB) is the most common solid, extracranial childhood tumor. "klf4 and lin28b were strongly dependent on N-myc for their continued expression with reductions in the N-myc null NSC at a similar level to that observed in neuroblastoma, while klf2 was only weakly regulated." (PMID 19495417, 2009). "Thus, N-Myc regulates expression of klf2, klf4, lif, and lin28b in human neuroblastoma." (PMID 19495417, 2009).
osteoarthritis (2 papers, 2019 to 2025). A noninflammatory degenerative joint disease occurring chiefly in older persons, characterized by degeneration of the articular cartilage, hypertrophy of bone at the margins and changes in the synovial membrane. "Overall, our gain-of-function (adenovirus-mediated overexpression of KLF2) approach in rat knee joint tissue clearly indicates that KLF2 is a potential therapeutic target for the treatment of osteoarthritis." (PMID 31827706, 2019).
periodontitis (2 papers, 2021 to 2022). An acute or chronic inflammatory process that affects the tissues that surround and support the teeth. "Decitabine reduces bone loss in a mouse model of periodontitis by inhibiting osteoclastogenesis through the upregulation of anti-inflammatory cytokines via KLF2 dependent mechanisms." (PMID 33671221, 2021). "We demonstrated that the DNA methyltransferase inhibitor, decitabine, ameliorates bone loss in a mouse model of periodontitis via a mechanism that involves the regulation of anti-inflammatory cytokine expression by KLF2." (PMID 33671221, 2021). "Nevertheless, our results provide a new insight into anti-inflammatory cytokine regulation via KLF2 and the possible therapeutic role of DNA methyltransferase inhibitors in the treatment of periodontitis." (PMID 33671221, 2021). "Taken together, our findings suggest that decitabine inhibits bone resorption in mice with periodontitis by upregulating KLF2 expression and thereby enhancing the expression of IL10 and TGFβ1." (PMID 33671221, 2021). "In particular, we examined whether decitabine modified the expressions of genes encoding anti-inflammatory molecules such as Krüppel-like factor-2 (KLF2), since these molecules inhibit osteoclast activity and thus periodontitis-associated alveolar bone loss." (PMID 33671221, 2021). "However, decitabine significantly increased KLF2 protein expression in mice with periodontitis as well as in control mice." (PMID 33671221, 2021). "JUN, FOS, KLF2, THBS1 and WIF1 were identified as key regulator in periodontitis and validated to be highly expressed in IPT through RT-qPCR." (PMID 36045361, 2022). "Five mRNAs, i,e., FOS, JUN, KLF2, WIF1, and THBS1, for further validation via RT-qPCR on 15 periodontitis and 15 healthy gingivae samples." (PMID 36045361, 2022).
retinoblastoma (2 papers, 2024 to 2025). A malignant tumor that originates in the nuclear layer of the retina. "Exosomal miR-92a-3p derived from retinoblastoma cells promotes angiogenesis by increasing endothelial cell migration and tube formation through downregulation of Krüppel-like factor 2 (KLF2), a key regulator of angiogenesis." (PMID 40002766, 2025). "The participation of miR-92a-3p in exosome-mediated angiogenesis was found in retinoblastoma by targeting transcription factor KLF2 which is able to modulate tumor proliferation and metastasis." (PMID 38255950, 2024).
splenic marginal zone B cell lymphoma (2 papers, 2022 to 2023). "Somatic KLF2 mutations involving the zinc finger domain are commonly found in splenic marginal zone B cell lymphoma (SMZL) although their role is incompletely understood." (PMID 36466816, 2022).
steatosis (2 papers, 2022 to 2024). Increased lipid within the cytoplasm of cells. "KLF2 has indeed been linked to steatosis and triglyceride accumulation in the liver." (PMID 36465560, 2022). "Our findings indicate that KLF2 promotes steatosis by upregulating SCAP expression and activating SREBP1 downstream targets that are involved in lipogenesis." (PMID 37949368, 2024). "Therefore, we overexpressed Klf2 in C36/− mice fed a normal diet and found that KLF2 induced steatosis as well as an increase in liver weight in CD36−/− mice in the fed stage." (PMID 37949368, 2024).
thyroid cancer (2 papers, 2023 to 2025). "It was shown that KLF2 knockdown enhanced cell propagation and invasion and migration in thyroid carcinoma." (PMID 37817224, 2023).
viral infection (2 papers, 2015 to 2020). "As summarized in this review, Tfh cell-related transcription factors including Bcl6, IRF4, STAT1/STAT4/STAT5, T-bet, TCF-1, LEF-1, TOX2, Bach2, FOXP1, and KLF2 are all involved in the virus infection." (PMID 32766317, 2020). "Our data also indicated for the first time in the context of viral infection that Tfh cells express KLF2 and Foxo1, which are inhibitory transcriptional factors responsible for arresting CXCR5 and Bcl-6 expression." (PMID 26640894, 2015).
Achalasia (1 paper, 2023). A disorder of esophageal motility characterized by the inability of the lower esophageal sphincter to relax during swallowing and by inadequate or lacking peristalsis in the lower half of the body of the esophagus. "Analysis of DEGs showed the common upregulations of SFPQ, KLF2, and CYBA and common downregulations of JUNB, FAM118A, and C21orf33 in peripheral blood lymphocytes of achalasia." (PMID 37542039, 2023).
acute myeloid leukemia (1 paper, 2024). Acute myeloid leukemia (AML) is a group of neoplasms arising from precursor cells committed to the myeloid cell-line differentiation. "Notably, in Wang’s paper, KLF2 is reported to be positively involved in the DT-13-induced acute myeloid leukemia cell apoptosis and differentiation." (PMID 39014479, 2024).
acute promyelocytic leukemia (1 paper, 2013). An aggressive form of acute myeloid leukemia (AML), characterized by arrest of leukocyte differentiation at the promyelocyte stage, due to a specific chromosomal translocation t(15;17) in myeloid cells. "Furthermore KLF2 expression in acute promyelocytic leukemia (APL) can be restored by ATRA treatment." (PMID 23565812, 2013).
age-related macular degeneration (1 paper, 2025). Age-related loss of vision in the central portion of the retina (macula), secondary to retinal degeneration. "CDK8 can promote Vascular Endothelial Growth Factor (VEGF) expression via the β-catenin-KLF2 axis, thereby driving angiogenesis, which is implicated in retinal diseases such as diabetic retinopathy (DR) and age-related macular degeneration (AMD) through increased VEGF signaling." (PMID 41427248, 2025).
Alzheimer disease (1 paper, 2021). A progressive, neurodegenerative disease characterized by loss of function and death of nerve cells in several areas of the brain leading to loss of cognitive function such as memory and language. "In addition, downregulation of KLF2 by microRNA-25 was unfolded to aggravate hippocampal neuron injury induced by Amyloid-β1-42 via the Nrf2 signaling pathway in a mouse model with Alzheimer’s disease." (PMID 34462420, 2021).
amyloid (1 paper, 2018). "Amyloid beta plaques, a hallmark of Alzheimer’s, decrease KLF2 levels in cerebral ECs; and overexpression of KLF2 protects against amyloid-induced oxidative stress." (PMID 29459900, 2018).
anemia (1 paper, 2023). A reduction in the number of red blood cells, the amount of hemoglobin, and/or the volume of packed red blood cells. "Moreover, Klf2-deficient embryos die due to embryonic heart failure but not from anemia or structural vascular defects." (PMID 37583551, 2023).
aneurysm (1 paper, 2019). Bulging or ballooning in an area of an artery secondary to arterial wall weakening. "We hypothesized that Klf4, Klf2, and Zfp148 are important for phenotypic modulation and one mechanism of phenotypic modulation during aneurysm formation is by the activation of autophagy." (PMID 31025534, 2019). "In summary, these studies represent only one possible mechanism for Klf4, Klf2, and Zfp148 as activators of autophagy during AAA formation and lead further credence to the importance of autophagy, Klf4, Klf2, and Zfp148 in broad significance for the overall aneurysm phenotype." (PMID 31025534, 2019).
Arrhythmia (1 paper, 2022). Any cardiac rhythm other than the normal sinus rhythm. "The downregulation of KLF2 (a shear stress-sensitive transcription factor) leads to oversensitivity of PChRs, increase in renal sympathetic nerve activity, development of oscillatory breathing, and propensity for arrhythmias in rabbits with congestive HF." (PMID 35492596, 2022). "Interestingly, increasing KLF2 expression with simvastatin treatment in rodent model limited the augmentation of peripheral chemosensitivity and improved respiratory variability, periodic breathing and arrhythmia index following coronary ligation." (PMID 35492596, 2022).
B cell deficiency (1 paper, 2022). A broad classification of disorders where circulating numbers of B lymphocytes are decreased or ineffective. "The other KLF2 variant positive family members have not presented with obvious primary infection susceptibility typical for B cell deficiency." (PMID 36466816, 2022).
brain injury (1 paper, 2022). Acute and chronic (see also brain INJURIES, CHRONIC) injuries to the brain, including the cerebral hemispheres, CEREBELLUM, and brain STEM. "These various downstream signaling molecules, therefore, may be related to KLF2-medatied protection against hypoxic-ischemic brain injury in neonatal rats, and thus require much more elaboration in future investigations." (PMID 35091544, 2022).